MIR4464 (microRNA 4464)
Synonyms: hsa-mir-4464; mir-4464
Gene: MicroRNA gene on chromosome 6 (90,312,742 to 90,312,833, forward strand). Ensembl gene ENSG00000266760.
Diseases named in the same sentence as MIR4464 in open-access papers:
MIR4464 is named in the same sentence as 1 disease in open-access papers, as found by Europe PMC text mining. Sharing a sentence is not in itself a finding about the gene and the disease. The quoted sentences say what the papers report.
leukemia (1 paper, 2018). A malignant (clonal) hematologic disorder, involving hematopoietic stem cells and characterized by the presence of primitive or atypical myeloid or lymphoid cells in the bone marrow and the blood. "We assume that all three genes located between MAP3K7 and CASP8AP2 (GJA10, BACH2, MIR4464) and a variable number of adjacent genes are co-deleted in these leukemias." (PMID 29914415, 2018).